GAS6 (growth arrest specific 6)
Diseases named in the same sentence as GAS6 in open-access papers (continued):
Sharing a sentence is not in itself a finding about the gene and the disease.
tumor (continued). "The MDK/LRP1, MDK/ALK, GAS6/MERTK, and GAS6/AXL were identified as potential ligand-receptor pairs involved in the interactions between fibroblasts/endothelial cells and tumor cells." (PMID 37733241, 2023). "Roles for Gas6/AXL signaling in cancer development and progression, and shaping of the tumor microenvironment are gradually being revealed." (PMID 37265798, 2023). "Gas6 binds to the TAM receptor on the surface of NK cells (natural killer cells) and inhibits their anti-tumor immune effects." (PMID 38259511, 2023). "As Gas6/AXL signaling triggers an immunosuppressive tumor microenvironment, the functions of diverse immune cells and the overall makeup of the tumor immune microenvironment are modified in this process." (PMID 37265798, 2023). "Mechanistically, Gas6/Axl signaling promotes fibrosis through HSC hepatic stellate cell (HSC) activation, and upregulation of Axl in HCC fosters tumor progression by affecting HCC plasticity and remodeling the tumor environment." (PMID 37532736, 2023). "Of note, Gas6 has a higher affinity for AXL receptors than for Mertk or Tyro3 receptors, which were expressed at lower levels on tumor macrophages." (PMID 37798557, 2023). "The present section mainly summarizes the cell-dependent role of Gas6/AXL in the TME in malignant cells, e.g., the roles of immune and vascular smooth muscle cells (VSMC) on tumor development." (PMID 37265798, 2023). "The interaction pairs via SPP1, RARRES2, NECTIN3, LGALS9, and LAMB1 showed increased signaling in the autophagy-high tumor cells, while SEMA3C, PTN, ICAM1, GAS6, and CSF1 showed decreased signaling compared with those in the autophagy-low tumor cells." (PMID 36830707, 2023). "Gas6/AXL signaling activates Src, local adhesion kinase (FAK) and NFκB to promote proliferation in nerve sheath tumor cells." (PMID 37265798, 2023). "The Gas6/AXL pathway regulates angiogenesis, immune-related molecular markers and the secretion of certain cytokines in the tumor microenvironment, and also modulates the functions of a variety of immune cells." (PMID 37265798, 2023). "After stopping gemcitabine treatment, metastatic tumor cells secrete CXCL1 and CXCL2 to attract neutrophils that express growth arrest-specific 6 (Gas6) protein, a ligand of AXL receptor on metastatic tumor cells, resulting in tumor regrowth and progression." (PMID 37173915, 2023). "Ligand–receptor pairs, such as PROS1-AXL, NAMPT-INSR, MDK-LRP1, MDK-ALK, GAS6-MERTK, and GAS6-AXL, between endothelial and tumor cells exhibited a higher communication possibility than that between endothelial cells and thyrocytes." (PMID 37733241, 2023). "Upon binding to its ligand GAS6, AXL regulates cell signaling cascades and cellular communication between various components of the tumor microenvironment, including cancer cells, endothelial cells, and immune cells." (PMID 35572601, 2022). "Given that patients with tumor AXL- and stromal Gas6-positive tumors had significantly lower five-year disease-free survival rates than the double negative group, it was concluded that Gas6 is involved in poor clinical outcomes." (PMID 35053080, 2022). "The expression of ANXA5, GAS6, and MAPK1 in the tumor cells was significantly higher than that in the normal cell line." (PMID 36212395, 2022). "SHH from tumor cells in turn induces expression of growth factors insulin growth factor 1 (IGF1) and growth arrest-specific 6 (GAS6) in PSCs." (PMID 35159011, 2022). "Stimulation with EGF or GAS6 enhanced downstream signaling in parental EGFRMT cells, and EGFR and MERTK shared common signaling pathways that promote tumor cell survival and proliferation, including PI3K/AKT and MAPK/ERK pathways." (PMID 35708914, 2022). "At the same time, it is worth noting that the TAM receptor and their two ligands, GAS6/ PROS1, have been reported to abnormally express in various tumor microenvironments or promote tumor growth and infiltration." (PMID 35033201, 2022).
tumor (continued). "The present study further demonstrates that the combination treatment modulates the expression of the tumor receptor signaling molecules, including TGF-β/TβR-2, AXL/Gas6, and Wnt/FZD/β-catenin/GSK-3β, in LLC1 tumor tissues." (PMID 36547898, 2022). "In the current study, Gas6 expression was decreased in KIRC tumor tissues, and Gas6 expression was decreased with tumor grades 1–3 and tumor metastasis." (PMID 36059952, 2022). "Among the genes involved in the significant interactions, GAS6 and LGALS9 were expressed at higher levels in C4 than in the other tumor clusters." (PMID 35892844, 2022). "Activation of Axl by GAS6, MTT, and cell cloning detected an increased proliferation of tumor cells." (PMID 35310910, 2022). "For example, BMSCs, one subtype of bone stromal cells, can either promote or impede the progression of tumor dormancy by secreting BMP7, TGFβ2, GAS6." (PMID 34712663, 2021). "The annexin II-mediated link between tumor cells and osteoblasts promotes the expression of tyrosine kinase receptors AXL, Sky, and Mer on tumor cells, whose ligand is GAS6." (PMID 34212564, 2021). "Extracellular domains of MERTK and AXL fused to the Fc domain of immunoglobulin G1 can also titrate GAS6 and thereby block GAS6-dependent signaling through the TAM kinases, resulting in decreased tumor metastasis." (PMID 34830794, 2021). "Collectively, these findings indicate that proangiogenic factors (e.g., Gas6 and VEGFA) and different subtypes of VEGF promote tumor angiogenesis through different mechanisms." (PMID 34966744, 2021). "A driving force in this cascade is tumor cell-derived IL-10 and M-CSF, which attracts and modifies circulating lymphocytes in the TME to secrete Gas6 into the TME." (PMID 35127700, 2021). "Perhaps, in the bloodstream where the concentration of PROS1 is much higher than GAS6, TYRO3 is primarily responsible for sEVs-induced pathways in circulating tumour cells." (PMID 34638349, 2021). "In our study, Gas6 is present in TPC‐EVs and instigated EPC recruitment for tumour revascularization via activating the Axl pathway." (PMID 34035882, 2021). "Although the tumor cell expression of TGF-β mediated by the Gas6-Axl pathway can sustain quiescence, TGF-β also has well established functions in promoting tumor cell growth in addition to modulating bone remodeling, angiogenesis and immune cell function." (PMID 33805598, 2021). "The interactions between the tumor and host immune cells in the tumor microenvironment can induce the expression of AXL and GAS6 to promote a cancerous microenvironment." (PMID 34778071, 2021). "Activation of MerTK signaling by its ligands Growth Arrest-Specific 6 (Gas6) and Protein S1 (PROS1) promoted cell proliferation and metastasis and suppressed the immune response in tumour microenvironment." (PMID 33139930, 2021). "CAFs which overexpress hMENAΔv6, an isoform of the actin-regulating protein hMENA, seem to secrete in the microenvironment with high levels of GAS6, the AXL ligand on tumor cells." (PMID 33182542, 2020). "In summary, these novel selective compounds not only establish the integral role of GAS6 and TAM receptors in regulating tumor dormancy but also serve as tools for further development of selective TAM inhibitors." (PMID 32503267, 2020). "Currently, there are plentiful experimental studies regarding GAS6- and TAM-targeted treatments, which have been confirmed to reduce tumor progression in vitro." (PMID 32346605, 2020). "While the role of Gas6 and Axl in cancer has been broadly reviewed elsewhere, it is becoming increasingly clear that this signaling axis also impacts non-neoplastic cell populations which may be of particular interest when viewed in the context of the tumor microenvironment." (PMID 32660000, 2020). "To get insight into SWINGN impact on GAS6 regulation in cancer we analyzed the correlation between SWINGN and GAS6 expression across samples of different tumor types of The Cancer Genome Atlas (TCGA)." (PMID 32071317, 2020).
tumor (continued). "Expression of additional mediators of tumor growth, including MMP9 and Gas6 is also induced by gal-8." (PMID 32355198, 2020). "Here, we report a novel function of hMENA/hMENAΔv6 isoforms in tumor‐promoting CAFs and in the modulation of pro‐tumoral cancer cell/CAF crosstalk via GAS6/AXL axis regulation." (PMID 32909687, 2020). "Taken together, these results suggest that myeloid cells represent a constitutive source of Gas6 and PROS1 in the tumor microenvironment." (PMID 33101282, 2020). "The findings of the present research confirm the results of the recent studies about overexpression of GAS6 and AXL in tumor tissues." (PMID 31700829, 2019). "Factors secreted by the microenvironment, such bone morphogenetic proteins (BMPs) and growth arrest-specific 6 (GAS6) produced by osteoblasts, can directly inhibit disseminated tumor cell (DTC) proliferation." (PMID 31330946, 2019). "Activation of Gas6/TAM signaling in cancer cells promotes their proliferation and inhibits their apoptosis while the signaling pathway can lead to a tumor-promoting microenvironment, for example, suppressing anti-tumor effects by natural killer (NK) cells." (PMID 30700007, 2019). "We propose that TAM secretome, including Gas6, contributes to this aggressiveness through activation of the AXL receptor, which is overexpressed on GemOE/TNBC tumor cells." (PMID 31844158, 2019). "It was suggested that tumor-related genes such as NNMT, FLI1, GAS6, IncRNA CCAT1, PDCD1LG2, and CD274 are key regulators in tumor-like transformation under long-time exposure to P. gingivalis." (PMID 30671195, 2019). "The autocrine and paracrine loops of AXL and its ligand Gas6 may enhance the activity and proliferation of endothelial cells, regulate the function of integrin, and promote the migration and survival of endothelial cells and tumour cells through RAC and AKT signalling." (PMID 31684958, 2019). "GAS6 and PROS1 were both found to be expressed by tumor cells, and led to autocrine activation of the receptors, promoting oncogenic characteristics." (PMID 31775787, 2019). "Recent studies have found that GAS6/TAM interaction plays an important part not only in tumor cells for its biological functions, but also have a marked impact on tumor microenvironment and cancer metastasis." (PMID 31028135, 2019). "In recent years, the roles of Gas6/TAM signalling in cancer cells and the tumour microenvironment have been studied, and some progress has made in targeted therapy, providing new potential directions for future investigations of cancer treatment." (PMID 29386018, 2018). "OBs also secrete factors such as growth arrest specific 6 (GAS6), which binds to the receptor tyrosine kinase AXL, activating it and thus promoting tumor cell dormancy." (PMID 29461491, 2018). "We indicate that the network-based on hMENA/Gas6/Axl expression may represent novel prognostic and therapeutic targets and the pattern of hMENA isoform expression in both tumor cells and CAFs may reveal tumor mesenchymal traits identifying cancer subtypes for tailored therapies." (PMID 30400822, 2018). "A recent study showed that CAF-derived GAS6, an AXL ligand, can activate AXL and promote tumor cells migration." (PMID 29946230, 2018). "Gas6/TAM is required for proliferation and migration of cancer cells, and several studies have shown that knockdown of Axl and Mer inhibits tumour cell proliferation and induces apoptosis." (PMID 29386018, 2018). "In this review, we introduce the Gas6 and TAM receptors and describe their involvement in different cancers and discuss the roles of Gas6 in cancer cells, the tumour microenvironment and metastasis." (PMID 29386018, 2018). "At the same time, in a bidirectional interaction, OSCC cells, that also produce Gas-6, polarize TAM toward a tumour-promoter phenotype." (PMID 28381274, 2017). "Numerous experimental studies on Gas6- and TAM-targeted treatments have shown reduced tumour progression, almost all of which have been conducted in vitro." (PMID 28333143, 2017).
tumor (continued). "With the facilitation of bioinformatics analyses and validation, we identified some tumor-related genes, such as NNMT, FLI1, GAS6, lncRNA CCAT1, PDCD1LG2, and CD274, as the key regulators in the present tumor-like transformation model." (PMID 28286742, 2017). "This line of reasoning led us to investigate the relationship between GAS6 expression, which would be expected to impact signaling through both MERTK and AXL, and tumor progression in GBM using the TCGA database." (PMID 27783662, 2016). "As IGF1 and GAS6 are secreted by activated PSCs, we investigated the dependency of IGF1R and AXL activity on the PSC-induced tumor cell phosphoproteome." (PMID 27087446, 2016). "In summary the role of Gas6/protein S and the TAM receptors remains controversial in solid tumors with different roles depending on the tumor entities." (PMID 27486820, 2016). "Immunohistochemical staining of tumor tissues has shown that AXL, GAS6 and HIF-1 are coexpressed, supporting the concept that hypoxia and HIF activity is a mechanism for AXL upregulation in human cancers." (PMID 27834845, 2016). "GAS6 and its receptors (Tryo 3, Axl, Mer or “TAM”) are known to play a role in regulating tumor progression in a number of settings." (PMID 27028863, 2016). "In conclusion, we report that Gas6 level is significantly increased in OSCC patients, in serum and tumor tissue, and elevated serum Gas6 is related to late TNM stage and poorly differentiated tumors." (PMID 26207647, 2015). "High tumour stage (TNM) was predictive for poor survival, while CD68 and Gas6 protein expression correlated with a favourable outcome." (PMID 21794149, 2011). "Backward variable selection in a Cox model verified tumour size and histology, and the three molecular markers CD68, Gas6, and Notch3, as relevant factors." (PMID 21794149, 2011). "The Gas6/AXL pathway has also been shown to protect epithelial/endothelial cells from apoptosis and has been suggested to play an important role in tumor vascularization." (PMID 19558675, 2009). "Importantly, the authors also demonstrated that tumour-related genes, such as NNMT, FLI1, GAS6, lncRNA CCAT1, PDCD1LG2, and CD274, were key regulators of neoplastic transformation in response to a low multiplicity of oral pathogen infection." (PMID 41228271, 2025). "Higher levels of GAS6 mRNA were observed in patients with residual disease following initial cytoreductive surgery as compared to patients without residual tumor mass ​." (PMID 40813689, 2025). "Beyond the use of Protein S and Gas6, an antibody-based delivery system localizes an anti-tumor drug to the TME without the adverse effects of whole-body treatment exposure." (PMID 40069722, 2025). "From these data, we concluded that tumor cell-intrinsic Gas6/Axl signaling does not control proliferation but augments invasiveness and the metastatic potential of malignant hepatocytes in vitro and in vivo." (PMID 38673795, 2024). "Compared to CPVLlow TAMs, CPVLhi TAMs received more GAS6 signals from fibroblasts, endothelial cells and dendritic cells, also, more ANXA1 signals from neutrophils, monocytes, dendritic cells, fibroblasts, endothelial cells, and tumor cells." (PMID 39776914, 2024). "TAMs constrain NK cells’ anti-tumour functions by downregulating activating receptors (NKG2D, 2B4) in NK cells or by expressing distinct immunosuppressive ligands such as PD-L1, GAL9, CD155, GAS6, and TGFβ." (PMID 37313600, 2023). "Growth arrest-specific protein 6 (GAS6) is a secreted vitamin K-dependent protein that binds to the receptor AXL and promotes tumor neovascularization by regulating endothelial cell function, the activation status of integral proteins, and the expression of pro-angiogenic factors." (PMID 36816799, 2023). "In the independent validation set, we found regulatory chains with GAS6, TIMP1, SPP1, and VEGFA as ligands, which was consistent with our findings above, indicating that these regulatory relations may be ubiquitous in tumor cells and macrophages." (PMID 37189418, 2023).
tumor (continued). "Notably, MDK/LRP1, MDK/ALK, GAS6/MERTK, and GAS6/AXL between fibroblasts and tumor cells exhibited a higher communication possibility than that between fibroblasts and thyrocytes." (PMID 37733241, 2023). "Additionally, tumor cells upregulate AXL and Gas6 expression in presence of monocyte myeloid-derived suppressor cells (M-MDSCs) and polymorphonuclear myeloid-derived suppressor cells (PMN-MDSCs)." (PMID 37265798, 2023). "In human CRC specimens, GAS6 overexpression is detected in more than 70% of CRC by IHC, and is positively correlated with less differentiated histological grading, advanced lymph nodes status, and tumor stage." (PMID 37958942, 2023). "The GAS6/AXL axis regulates many tumor immune-related biomolecules, e.g., major histocompatibility complex I (MHC-I) and programmed death ligand-1 (PD-L1) in tumor cells, and the levels of secreted anti-inflammatory cytokines such as IL-4, CCL3-5 and granulocyte colony-stimulating factor (G-CSF)." (PMID 37265798, 2023). "GAS6-CAR-T cells were also demonstrated to recognize mouse TAM and kill mouse tumor cell lines, but did not cause any significant side effects in xenograft mice." (PMID 37475048, 2023). "Furthermore, the TAM signaling pathway is widely active in various body tissues, including in tumour cells that upregulate TAM signaling through autocrine and paracrine PROS1 or GAS6, thereby facilitating a more favourable environment for tumour growth." (PMID 36203174, 2022). "In addition, TAMs are also considered to be the main source of multifunctional protein Gas6, and the activation of Gas6-Axl signaling pathway has a positive effect on EMT and tumor metastasis." (PMID 36611857, 2022). "Activation by phosphatidyl serine (PtdSer) externalized on apoptotic cells complexed with the protein ligands protein S1 (PROS1) or growth arrest specific factor 6 (GAS6) leads to activation of downstream pathways, including PI3K/AKT and MAPK/ERK, and promotes tumor cell survival." (PMID 35708914, 2022). "In summary, the GAS6/AXL signaling may promote macrophage, monocyte, and MDSC infiltration, decrease tumor abundance of mature DCs, NK CD4+ and CD8+ T-cells." (PMID 35572601, 2022). "PROS1 and GAS6 are produced by tumor cells and nonneoplastic cells in TME, which function as bridging molecules that are the physical link between MerTK and Phosphatidylserine (PtdSer)." (PMID 36497444, 2022). "Notably, GAS6 overexpression was detected in cultured CAFs overexpressing hMENA, whereas hMENA silencing decreased GAS6 expression and reduced NSCLC tumor cell invasiveness." (PMID 36422541, 2022). "Similarly, GAS6 and PROS1 were significantly increased, and there was a trend toward increased MERTK expression in tumor biopsies from patients with EGFRMT NSCLC after treatment with OSI." (PMID 35708914, 2022). "Increasing evidence showed that activated CAFs could regulate tumor cell invasion and growth by secreting soluble factors (exosomes, HGF and GAS6) and depleting metabolic factors (lactate, amino acid, alanine, and aspartate)." (PMID 36389798, 2022). "Interaction between GAS6 expressed by CAFs and AXL expressed by myeloid cells changes the interaction levels of PD-L1 and MHC-I, increases the secretion of cytokines involved in immune suppression, and decreases the tumor-infiltrating CTL population." (PMID 35892844, 2022). "IGF1 and GAS6 act as paracrine-reciprocal signals for activating the receptor tyrosine kinases IGF1R and AXL (“anexelenko”, which means “uncontrolled” in Greek), respectively, in tumor cells." (PMID 35159011, 2022). "The presence of Gas6/TAM inhibits cell death and leads to proliferation of tumor cells." (PMID 35760058, 2022). "Quantitative RT-PCR analysis of 8 tumor xenograft-derived cell lines showed that none had lost expression of either GAS6 or AXL; in fact, 6 of 8 had acquired significantly increased expression of MERTK (also activated by Gas6) and KDR." (PMID 34292953, 2021).